STAT3 (signal transducer and activator of transcription 3)
Diseases named in the same sentence as STAT3 in open-access papers (continued):
Sharing a sentence is not in itself a finding about the gene and the disease.
lung carcinoma (continued). "Some of these direct and indirect targets are shared in different cancers, including PD-L1 (melanoma, medulloblastoma and lung cancer), Rb (prostate and MTC), STAT3 (PCa and MTC) and talin (breast and prostate)." (PMID 37993880, 2023). "Fibroblasts, isolated from human lung cancer tissues, were found to actively secrete IL-6 and enhance metastatic activity in human lung cancer cell lines through JAK2 and STAT3 signal transduction activation." (PMID 36986550, 2023). "Collectively, these results indicate that YHO-1701 effectively suppresses cell adaptation to ALK-TKIs driven by STAT3 re-activation and induces apoptosis in residual ALK-rearranged lung cancer cells." (PMID 35228642, 2022). "Related literature reports that IFN-γ can promote lung cancer progression via the JAK/STAT3 signaling pathway and PI3K/AKT signaling pathway in lung carcinomas." (PMID 36091807, 2022). "In lung cancer, mesenchymal stem cells can enhance tumorigenesis by activating IL-6/JAK2/STAT3 pathway." (PMID 36591515, 2022). "SH2B3 interacts with Janus kinase 2 (JAK2) and Src homology region 2-containing protein tyrosine phosphatase 2 to inhibit JAK2/STAT3 and PI3K/AKT signaling pathway-mediated anoikis in lung cancer." (PMID 36230714, 2022). "Therefore, inhibiting Stat3 activation may be an effective way to treat lung cancer." (PMID 35178453, 2022). "For example, TRIM32 positively regulates p-STAT3 levels in lung cancer, and TRIM52 promotes SHP2 ubiquitination, consequently inactivating STAT3 signaling in colorectal cancer." (PMID 36288633, 2022). "It has also been reported that lupeol, a substance abundant in vegetables, suppresses STAT3 activation, which is upregulated in KRAS mutant lung cancer." (PMID 36348317, 2022). "Silencing KLF3 contributes to lung cancer metastasis and the EMT process by regulating the STAT3 signaling pathway." (PMID 35311620, 2022). "PI through PGG impedes STAT3 activation but activates ERK signaling, which plays a central role in en routing lung cancer cells toward apoptosis." (PMID 35928273, 2022). "Recent studies on lung cancer have also shown that HDAC7 has positive effects on tumorigenesis and cell growth via inhibition of Stat3 and plakoglobin." (PMID 35277183, 2022). "Treatment with BB1608, a STAT3 inhibitor, results in decreased G9a and HER3 expression and sensitizes lung cancer cells to EGFR tyrosine kinase inhibitor." (PMID 35740522, 2022). "According to in vitro and in vivo research, KLF3 inhibition accelerates lung cancer EMT and promotes lung cancer metastasis through the STAT3 signalling pathway." (PMID 35345512, 2022). "Besides, deletion of STAT3 could enhance KRAS-driven lung cancer development." (PMID 36619616, 2022). "Here, we evaluated the expression of NF-κB, AICDA, Akt, IL-6, Jak2, and Stat3 by EGFR-TKI-resistant lung adenocarcinoma (LAC), and found that NF-κB and AICDA are major players in the acquired resistance of lung cancer to TKIs." (PMID 35740609, 2022). "One study suggests that STAT3-regulated CD5 expression on B cells drives IL-6 signaling and disease progression in lung cancer." (PMID 35406557, 2022). "Thus, we tested to determine whether osteoclast-derived IL-19 activates STAT3 in lung cancer cells." (PMID 36006737, 2022). "In this study, we explored the positive correlation of MALAT1 with STAT3 and FUT4 activity in paclitaxel resistant A549 (A549/T) lung cancer cells." (PMID 35281907, 2022). "The current work sought to provide novel insights into the functional response of MALAT1 and efficacy of common members of SLs (ALT and Brv-A) in paclitaxel-resistant lung cancer, vis-à-vis MALAT1/STAT3 and MALAT1/FUT4 axis." (PMID 35281907, 2022). "CAFs isolated from lung cancer tissue promote metastasis by secreting IL-6, which activates JAK2 and STAT3 signaling and also induces EMT via increasing vimentin expression in lung cancer cells both in vitro and in vivo." (PMID 36620544, 2022).
lung carcinoma (continued). "For example, B7-H4 upregulation induces immune escape of lung cancer and non-small cell lung cancer cells through MEK/ERK and PD-1/Stat3 signaling pathways." (PMID 34818980, 2022). "In summary, our study is the first to illustrate the crucial roles of SH2B3 in lung cancer and reveals that TGF-β1/SH2B3 axis regulates the anoikis resistance and EMT process of lung cancer cells via JAK2/STAT3 and SHP2/Grb2/PI3K/AKT signaling pathways." (PMID 35589677, 2022). "The mechanisms regarding IL‐17A in PF, inflammation, or lung cancer include a variety of signalling pathways, such as TGF‐β, PD‐1/STAT3, JAK2, and NF‐κB signalling." (PMID 36308405, 2022). "Chen and colleagues found that the inhibition of ATM using specific ATM inhibitor CP466722 or siRNA reduced JAK/STAT3 signaling and PD-L1 expression, thus inhibiting the EMT and metastatic potential of cisplatin-resistant lung cancer cells." (PMID 36559280, 2022). "Constitutive activated STAT3 has been found in various cancers, including ESCC, colorectal cancer, lung cancer, and gastric cancer." (PMID 36225196, 2022). "It has been reported that transthyretin, a secreted protein downstream of STAT3, could promote oncogenic gene activation, enhance cytokine function in the tumor microenvironment as well as increase the production of reactive oxygen species to facilitate the progression of lung cancer." (PMID 36338720, 2022). "TADC-derived AMPHIREGULIN induces STAT3 and AKT activation, which increases the expression of the EMT markers SNAIL and TWIST, indicating that the collaboration of STAT3 and AKT plays a crucial role in TADC-mediated chemoresistance in lung cancer." (PMID 36359776, 2022). "In previous study, the effect of ALT is investigated to reduce resistance of doxorubicin in A549 lung cancer cells via targeting MDR1 and STAT3." (PMID 35281907, 2022). "Mechanistically, α5 nAChR mediates the Stat3-Jab1/Csn5 and TGF-β1/Smad signaling pathways to promote metastasis and EMT of lung cancer cells." (PMID 36284268, 2022). "Chen found that Huaier inhibited lung cancer proliferation and metastasis through MTDH, JAK2/STAT3, and MAPK." (PMID 35470770, 2022). "HMA inhibits the growth of A549 lung cancer cells, which is related to the induction of apoptosis and inactivation of IL-6/JAK2/STAT3 signaling pathway." (PMID 36591515, 2022). "Stabilized c-Met is bound to its ligand and activates downstream signaling pathways, including those of Akt, signal transducer and activator of transcription 3 (STAT3), and ERK, which leads to lung cancer cell growth, proliferation, and survival." (PMID 35631459, 2022). "In lung cancer metastasis, CD109 expression led to the activation of the Jak‐Stat3 signalling pathway." (PMID 36134447, 2022). "It has been shown that the activation of STAT3 upregulates the expression of YKL-40, thereby promoting the occurrence and progression of lung cancer." (PMID 35237278, 2022). "Granzyme B was considered a hydrolase enzyme leading to tumor cell apoptosis but IFNγ induced STAT3-mediated PD-L1 and MCL1 expression in EGFR-positive lung cancer cells." (PMID 34685495, 2021). "Here, we identified DGG-100629 as a drug for the treatment of lung cancer via its suppression of DDIAS expression and inactivation of STAT3 signaling." (PMID 33859351, 2021). "But EGFR-resistance and downstream signaling gene STAT3 activation contributes to cell proliferation, anti-apoptosis, and resistance to CD8+ T cells in EGFR-positive lung cancer." (PMID 34685495, 2021). "Some experimental studies indicate that SIN is useful for the treatment of gastric carcinoma, lung cancer and breast cancer through regulating PI3K/AKT/Wnt, JAK/STAT3, JNK, and MEK/ERK signaling pathways." (PMID 34179090, 2021).
lung carcinoma (continued). "STAT3 curbs the RECK expression and increases the activity of MMP-2 and MMP-9 in lung cancer cells by up-regulation of miR-92a, promoting the malignant biological behavior of cells." (PMID 34790697, 2021). "Another interesting link, although only described in lung cancer, is the positive feedback loop composed of miR-199a-5p/HIF1-α and STAT3." (PMID 35008579, 2021). "Here, we examine the role of STAT3 in TKI-resistance and choose gefitinib as a representative EGFR-TKI inhibitor in this study due to its wide application in lung cancer treatment." (PMID 33391507, 2021). "An additional explanation regarding the favorable prognostic role of ASS1 expression by lung cancer cells comes from a recent study, suggesting that ASS1 is essential to block cancer cell invasion through STAT3 pathway inhibition." (PMID 34344457, 2021). "Collectively, our findings demonstrate that the combination of SH003 and DTX is a potential treatment strategy to inhibit the growth of lung cancer, by targeting the EGFR and STAT3 pathways." (PMID 34445110, 2021). "In lung cancer, MPC1 works with mitochondrial signal transducer and activator of transcription 3 (mito-STAT3) to reduce cytoplasmic STAT3." (PMID 34059057, 2021). "Silibinin appeared to target multiple cytokine (IFNγ, IL-1β, and TNF-α)-induced signaling pathways such as the signal transducer and activator of transcription 3 (STAT3) to ultimately lower COX2 and iNOS expression in lung cancer cells." (PMID 34208282, 2021). "The role of protein arginine methyltransferase 5 (PRMT5) in Janus kinase (JAK)‐signal transducer and activator of transcription 3 (STAT3) signaling pathway and lung cancer cell proliferation is unveiled." (PMID 34026434, 2021). "Accordingly, inhibition of the IL6/STAT3 signaling pathway using an IL6 neutralizing antibody or JAK2/STAT3 inhibitor reverses fibroblast-induced invasion and migration of lung cancer cells." (PMID 34944848, 2021). "LncRNA UCA1 has been demonstrated to promote EMT and mediates acquired resistance to gefitinib in lung cancer cells through MAPK/ERK, AKT/mTOR, and STAT3 signaling pathways." (PMID 33931980, 2021). "Luteolin also inhibits TGF-1-dependent EMT in lung cancer cells by blocking the PI3K/AKT/NF-κB/Snail pathway and also inhibits IL-6-dependent EMT in pancreatic cancer through the prevention of STAT3 signaling." (PMID 34220337, 2021). "In human lung cancer cells and tissues, DDIAS expression is strongly correlated with the level of phospho-STAT3 Y705, which supports the role of STAT3 phosphorylation in lung tumorigenesis." (PMID 33859351, 2021). "Lung cancer invasiveness was increased through TAM-secreted IFN-gamma, which activated JAK/STAT3 and PI3K/Akt signaling in the cancer cells." (PMID 32283687, 2020). "A preclinical study demonstrated the combination of STING agonist (cGAMP or RR-CDA) with the indirect STAT3 inhibitor VEGFR2 was maximally effective for immunotherapy-resistant tumors in breast and lung cancer." (PMID 32972405, 2020). "Another important signalling mediator is a signal transducer and activator of transcription 3 (STAT3) that is persistently activated in about 50% of NSCLC primary cancers and lung cancer–derived cell lines like H197526." (PMID 32533048, 2020). "Sun and colleagues have also discovered that 2- hydroxy-3-methylanthraquinone can inhibit lung cancer cell growth and invasion by downregulating IL-6-induced JAK2/STAT3 pathways." (PMID 33299414, 2020). "Knocking down FAS promoted lung cancer cells growth through NFkB activation-mediated enhanced IL6 secretion and subsequent STAT3 activation." (PMID 32963220, 2020). "At the same time, STAT3 and COX-2 were identified as two core targets of BEL in lung cancer treatment." (PMID 33299414, 2020).
lung carcinoma (continued). "Previous studies have demonstrated that the suppression of STAT3 phosphorylation and VEGF expression, as well as inhibition of MMP-2 and MMP-9, contributes to alleviating the invasion and angiogenesis process of lung cancer cells by curcumin." (PMID 33511113, 2020). "The abnormally increased secretion of IL-6 was related to the regulation of growth and metastasis of lung cancer cells, and the activation of the IL-6/AK2/STAT3 pathway enhanced initiation of tumor in lung cancer." (PMID 32595734, 2020). "In addition, it could interact with the TGF-β and JAK2/STAT3 pathway in lung cancer." (PMID 32802874, 2020). "Enhanced STAT3 signaling induced by FGFR4 G388R was confirmed in vivo with the FGFR4Arg385 knock-in mice and transgenic mouse models for breast and lung cancers." (PMID 32393201, 2020). "Activation of the Src kinase and the subsequent phosphorylation of STAT3, which positively regulates cell cycle effectors, are supposed to be mediated by PGE2 in lung cancer." (PMID 32171274, 2020). "Through the STAT3 pathway, IL-22 which is secreted by CD4+ αβ and γδ T cells, stimulates oncogenic KRAS-driven lung cancer development by promoting a pro-inflammatory microenvironment." (PMID 33116132, 2020). "Cucurbitacin I (JSI-124) reduced the phosphorylation of STAT3 and JAK in Src-transformed fibroblast and in human lung carcinoma cells." (PMID 32545187, 2020). "To further demonstrate the relationship between STAT3 and FAS in NSCLC, we knocking down STAT3, FAS, or both of them in lung cancer cells." (PMID 32963220, 2020). "Taken together, the results of this study showed that 10-HDA induced cell cycle arrest and apoptosis in A549 human lung cancer cells through ROS-mediated MAPK, STAT3, NF-κB, and TGF-β1 signaling pathways." (PMID 33376719, 2020). "In conclusion, 10-HDA induced apoptosis and cell cycle arrest of A549 human lung cancer cells through ROS-mediated modulation of the MAPK, STAT3, NF-κB, and TGF-β1 signaling pathways, and it also induced eventual mitochondrial-dependent apoptosis." (PMID 33376719, 2020). "Consistent with our in vitro human lung cancer cell lines, DDIAS expression level was strongly correlated with STAT3 tyrosine phosphorylation." (PMID 31900385, 2020). "Brassinin downregulated the expression of STAT3-directed genes (phospho-STAT3, Ki-67, and CD31), suppressed proliferation and invasion, and induced apoptosis in the xenograft lung cancer (A549) mouse model." (PMID 32545187, 2020). "We established lung cancer A549 cell lines stably expressing HP1α, STAT3WT, STAT3Y705F, and sh RNAi constructs targeting STAT3 and HP1α, respectively, as well as controls." (PMID 32087696, 2020). "With regard to lung cancer, the JAK2/STAT3 pathway was also found to mediate the process of cancer metastasis." (PMID 31621555, 2020). "In the present study, we demonstrated that 10-HDA induces ROS-mediated apoptosis in A549 human lung cancer cells by regulating the MAPK, STAT3, NF-κB, and TGF-β1 signaling pathways." (PMID 33376719, 2020). "When administered intraperitoneally, the combination of paclitaxel and brassinin diminished tumor growth by the downregulation of phospho-STAT3, CD31, and Ki-67 in a xenograft lung cancer model." (PMID 32545187, 2020). "As one of the downstream effects of STAT3, increased COX-2 expression has been correlated with the occurrence, development, invasion, and acquisition of a metastatic phenotype in lung cancer." (PMID 33299414, 2020). "To evaluate the correlation between STAT3 activation and expression of DDIAS and PTPRM, we performed immunohistochemistry (IHC) on 40 human lung cancer tissues." (PMID 31900385, 2020).
lung carcinoma (continued). "Our findings suggest that compared with HEDMNQ, HHDMNQ had the stronger ability to inhibit the cell viability of lung cancer cells and induce apoptosis by regulating the ROS-mediated intrinsic pathway and MAPK/STAT3/NF-κB signalling pathways." (PMID 32849902, 2020). "Huaier Granule extract suppresses proliferation and metastasis in lung cancer cells by downregulating the MTDH, JAK2/STAT3, and MAPK signalling pathways." (PMID 32244796, 2020). "In this study, A549 lung carcinoma cells exposed to PM10 showed increases of IL-6 and phosphorylation of JAK1/JAK2/STAT3 signaling molecules." (PMID 33374928, 2020). "In the present study, we discovered that BEL can also inhibit lung cancer by inhibiting the expression of COX-2 and STAT3." (PMID 33299414, 2020). "In the human lung carcinoma model A549, CD24 expression increased the expression of p-STAT3 (Y705), p-FAK (Y925), and p-Src (Y416) via Src, therefore it is associated with a poor prognosis of cancer." (PMID 31614769, 2019). "In lung cancer, TNS4 was upregulated by EGF-mediated STAT3 activation and its aberrant expression increased cancer cell invasiveness." (PMID 31052206, 2019). "Recent studies have shown that IL-22 enhances proliferation and migration of lung cancer cells via the IL-22R1/AKT and IL-22R1/STAT3 signaling pathways." (PMID 31750252, 2019). "STAT3 is persistently activated in approximately 50% of NSCLC primary tumors and lung cancer-derived cell lines." (PMID 30838170, 2019). "AZD9150, an antisense oligonucleotide inhibitor of STAT3, inhibits STAT3 activation in ALCL and nonsmall cell lung cancer lines and demonstrates antitumor activity in lymphoma and lung cancer patient-derived xenograft models." (PMID 31861597, 2019). "In this study, we characterized the combination therapy of AZ628, the inhibitor of RAF, and BP-1-102, the inhibitor of STAT3, in KRAS mutant lung cancer." (PMID 31484165, 2019). "Research has reported that CAV1 regulates lung cancer’s apoptosis via STAT3 pathway, which suggests that CAV1 mediate STAT3 pathway in NSCLC." (PMID 31296840, 2019). "Recent studies have found that both STAT3 and STAT5 are activated in lung cancer cells and tissues, indicating functional roles for these proteins in lung cancer." (PMID 30872582, 2019). "To confirm the synergistic effect of RAF and STAT3 inhibitors, we evaluated their roles in the growth of KRAS mutant lung cancer cells by using AZ628 (2 μM) and BP-1-102 (10 μM)." (PMID 31484165, 2019). "Hsv2-miR-H9-5p increases lung cancer cell migration and invasion in vitro by directly targeting suppressor of cytokine signaling 2 (SOCS2), inhibiting Jak2 kinase activity and Jak2-signal transducer and activator of transcription 3 (STAT3) binding." (PMID 30813457, 2019). "BBI608, a STAT3 inhibitor, was a potential therapeutic agent that reduced the cell viability of EGFR-positive lung cancer cell lines." (PMID 31619200, 2019). "Next, to investigate any correlation between CFH expression and the expression of STATs in human normal lung tissues and lung cancer tissues, the transcription level of CFH was compared with STAT1, STAT3, and STAT4." (PMID 30987235, 2019). "In hepatocellular carcinoma and lung cancer, TGF-β can induce the expression of PD-L1 on the surface of DCs, which depends on the activation of STAT3." (PMID 30646912, 2019). "Taken together, our findings reveal a direct role of miR‐206 in regulating IL‐6/STAT3 pathway and contrarily activated IL‐6/STAT3 signalling mediates the miR‐206 maturation process in gefitinib‐resistant EGFR‐mutant lung cancer cells." (PMID 31507089, 2019).